CASP8 (caspase 8)
Diseases named in the same sentence as CASP8 in open-access papers (continued):
Sharing a sentence is not in itself a finding about the gene and the disease.
steatosis (9 papers, 2012 to 2026). Increased lipid within the cytoplasm of cells. "Caspase-8 activation is the characteristic of murine and human alcoholic liver disease (ALD), deficiency of Caspase-8 in hepatocyte (Casp8Δhepatocyte) alleviated steatosis and reduced hepatic triglyceride and free fatty acid (FFA) content in ALD mice model." (PMID 32849904, 2020). "Additional studies have demonstrated that liver proteins are targeted for degradation following liver injury/steatosis, including nerve growth factor as well as the CASP8 and FADD-like apoptosis regulator." (PMID 38237682, 2024). "Therefore, we next investigated whether depletion of Caspase-8 in hepatocytes may influence the progression of alcohol-induced steatosis." (PMID 29072704, 2017). "Based on the differential functions of RIP3 and Caspase-8 in controlling liver injury in response to MCD-diet feeding, we next tested their influence on the pathogenesis of steatosis and NASH-induced liver fibrosis." (PMID 24963148, 2014). "The steatosis was detected in glucose treated LO2 cells by overexpressing circ_0004535, and CASP8." (PMID 37957232, 2023). "Although Caspase-8 inactivation in hepatocytes did not exert a hepatoprotective effect after 8 weeks of alcohol feeding, we cannot exclude the possibility that reduced steatosis might be beneficial within a longer observational period as a result of decreased hepatic ROS production." (PMID 29072704, 2017).
atherosclerosis (8 papers, 2016 to 2026). A disease characterized by the build-up of fatty material and calcium deposition in the arterial wall resulting in partial or complete occlusion of the arterial lumen. "While the lipid profile of Casp8komac mice was more favorable with respect to atherosclerosis, this aligns with recent findings that caspase-8 deficiency in myeloid cells, coupled with Ripk3 knockout, results in lower plasma cholesterol levels." (PMID 40264785, 2025). "The study highlights the role of caspase-8 in atherosclerosis in tuning the balance between apoptosis and necroptosis." (PMID 40264785, 2025). "Expression of overlapping genes and FRGs (MRPS23, CASP8) were verified using qRT-PCR in normal, Atherosclerosis and Atrial Fibrillation patients." (PMID 40607061, 2025). "In this study, we aimed to investigate the role of necroptosis in the progression of atherosclerosis by silencing or inhibiting caspase-8 in mice or primary macrophages in order to promote a switch towards necroptosis." (PMID 40264785, 2025). "Apoptosis in atherosclerosis is well documented as an active programmed process of autonomous cellular dismantling including activation of apoptotic caspase-3, caspase-8, and caspase-9." (PMID 31871426, 2019). "In particular, CXCR4, ICAM-1, Tumor Necrosis Factor Alpha-Induced Protein 3 (TNFAIP3), and Caspase-8 (CASP8) genes that present a role in atherosclerosis development at different level and with different functions were considered." (PMID 30356351, 2018). "Taken together, our data indicate that ALA-SDT mediates the switch from necroptosis to apoptosis by activating the caspase-3 and caspase-8 pathways and may improve the prognosis of atherosclerosis." (PMID 26911899, 2016). "Thispromotes the development of atherosclerosis by exacerbating inflammation.Nonetheless, the NLRP3 inflammasome can also trigger apoptosis byactivating caspase-8 in macrophages, although it remains unknown whether thisfunction hinders the development of atherosclerosis." (PMID 39076616, 2022).
brain cancer (8 papers, 2003 to 2023). A primary or metastatic malignant neoplasm affecting the brain. "Treatment with BP triggered increased expression of Fas, which led to the activation of caspase-8 and -3 in malignant brain tumor in our previous study." (PMID 22470469, 2012). "In another study, treatment with γ-T3 activated the extrinsic apoptotic pathway in brain cancer cells through the upregulation of pro-apoptotic proteins, such as Bax, and TNF-related apoptosis-inducing ligand (TRAIL), Caspase-3, and Caspase-8 also induced cell cycle arrest at G0/G1 phase." (PMID 35889829, 2022).
chronic lymphocytic leukemia (8 papers, 2012 to 2023). "In chronic lymphocytic leukemia (CLL), honokiol causes apoptosis through activation of caspase 8, followed by caspase 9 and 3 activation." (PMID 22353783, 2012).
Crohn disease (8 papers, 2013 to 2025). A gastrointestinal disorder characterized by chronic inflammation involving all layers of the intestinal wall, noncaseating granulomas affecting the intestinal wall and regional lymph nodes, and transmural fibrosis. "Mechanistic studies revealed a proapoptotic TMEM219-mediated molecular signature in Crohn’s disease, which associates with Caspase-8 activation and ISC death." (PMID 40371646, 2025). "In Crohn’s disease, the decline of Paneth cell appears to be associated with caspase-8–mediated programmed necrosis." (PMID 33055426, 2020). "To study the impact of STAT1 on gastrointestinal inflammation with features of Crohn's disease, we deleted this transcription factor in the Caspase-8 mouse model (Casp8ΔIEC)." (PMID 34141714, 2021). "Recently, it was described that also patients with inherited caspase-8 deficiency may develop intestinal inflammation but the role of caspase 8-genetics in Crohn's disease is not fully established." (PMID 32351509, 2020).
depression (8 papers, 2016 to 2025). "Proteinsencoded by the TNFA, CASP8, TNR5, and VEGFA genes,which are associated with epilepsy, depression, and otherneuropsychiatric diseases, were found among regulators ofASM activity and transport." (PMID 38223851, 2023). "Note that amongthe regulatory proteins, caspase-8 (CASP8) and tumor necrosisfactor alpha (TNFA) were present and found to be associatedwith overrepresented diseases such as epilepsy, depression,dementia and other neuropsychiatric diseases." (PMID 38223851, 2023). "This network consisted of a number of molecules previously reported to be associated with depression (according to a PubMed search), such as CYP3A5, VAMP2, CSGALNACT1, CASP8, CRHR2, PKD2, and OXT." (PMID 26728011, 2016). "Additionally, air pollution can activate inflammatory response pathways (e.g., IL1RN, galectin-3, CLEC4D, CASP8), disrupting neurotransmitter balance and exacerbating neuronal inflammation, thereby increasing the incidence of depression." (PMID 40611827, 2025).
glaucoma (8 papers, 2019 to 2024). Increased pressure in the eyeball due to obstruction of the outflow of aqueous humor. "In glaucoma, caspase-8 is linked to RGC apoptosis, as well as glial activation and neuroinflammation." (PMID 38947028, 2024). "In astrocytes, overexpression of Stat3 or knockdown of IκKβ/p65, caspase-8, and mitochondrial uncoupling proteins (Ucp2) can reduce ganglion cell loss in glaucoma mouse models." (PMID 36466782, 2022). "For instance, overexpression of Stat3 or C3, knockdown of IκKβ/p65, caspase 8 and mitochondrial uncoupling proteins (Ucp2) in astrocytes may reduce ganglion cell loss in glaucoma patients in the future." (PMID 36466782, 2022). "Thus, besides RGC apoptosis, caspase-8 is engaged in various inflammation pathways linked to glaucoma as well." (PMID 34199494, 2021). "In addition, caspase-8 activation has been linked to inflammation in experimental models of glaucoma and inhibition of caspase-8 blocks inflammation and prevents death of RGCs." (PMID 31570110, 2019). "Taken together, these results identify the caspase-8-mediated inflammatory pathway as a potential target for neuroprotection in glaucoma." (PMID 38947028, 2024). "This study, stimulated by recent experimental findings implying caspase-8/cFLIP interaction in cell fate decisions in experimental glaucoma, assessed an essential role of cFLIP in the molecular regulation of glia-driven neuroinflammation." (PMID 38824526, 2024). "Recent experimental studies of neuroinflammation in glaucoma pointed to cFLIP as a molecular switch for cell fate decisions, mainly regulating cell type-specific caspase-8 functions in cell death and inflammation." (PMID 38824526, 2024). "Based on diverse biological functions of caspase-8, a recent study also searched for caspase-8 as a treatment target to ameliorate NF-κB-regulated inflammation signaling in experimental glaucoma." (PMID 34199494, 2021). "Taken together, therapeutic modulation of neuroinflammation by targeting astroglial NF-κB, or caspase-8, resulted in both structural and functional protection of RGCs in experimental glaucoma." (PMID 34199494, 2021). "Nevertheless, despite increased self-processing of caspase-8, deletion of cFLIP in astroglia could reduce proinflammatory responses in experimental glaucoma while maintaining astroglia survival." (PMID 38824526, 2024). "In light of this information, this study sought to determine whether deletion of cFLIP can eliminate caspase-8-mediated inflammatory responses of astroglia in experimental glaucoma." (PMID 38824526, 2024). "Caspase-8 is detected in the apoptotic RGCs in human and animal models of glaucoma." (PMID 36466782, 2022). "Likewise, cell type-specific analysis of experimental glaucoma detected cleaved caspase-8 in RGCs undergoing apoptosis." (PMID 34199494, 2021). "Moreover, caspase-8 activation has also been linked to microglia activation and inflammation in experimental models of glaucoma and inhibiting caspase-8 blocked inflammation and prevented death of RGCs." (PMID 31570110, 2019). "In the extrinsic pathway of RGC apoptosis in glaucoma, which can be triggered by the ligation of dead receptors, such as TNFR1 or Fas, caspase-8 plays an initiator role." (PMID 38824526, 2024). "The recent study exploring the molecular processes of glaucoma linked cFLIP to cell type-dependent differences in the biological activities of caspase-8, including apoptotic caspase-8 activity in RGCs and the non-apoptotic function of caspase-8 in glial inflammatory responses." (PMID 38824526, 2024). "Intriguingly, inhibition of the initiator caspase-8 suppressed JNK1 signaling in RGCs, besides preventing RGC apoptosis in experimental glaucoma." (PMID 34199494, 2021). "The key role of inflammation and inflammatory caspases, like caspase-8 (CASP8), in the pathogenesis of glaucoma induced via non-ischemic OHT injury has been recently shown." (PMID 37998361, 2023).
glaucoma (continued). "Cell type-specific diverse functions of caspase-8 in RGC apoptosis and astroglia-driven neuroinflammation may support its multitarget potential for glaucoma treatment." (PMID 34199494, 2021). "It should also be clarified whether apoptosis, if induced long-term, would specifically affect astroglia’s proinflammatory/neurotoxic states because these cells would be primed for caspase-8 expression and activities through TNFR, TLR signaling, or the inflammasome activation in glaucoma." (PMID 38824526, 2024).
Hypertension (8 papers, 2016 to 2025). The presence of chronic increased pressure in the systemic arterial system. "Overexpression of Cathepsin K in kidney mesangial cells indirectly increases peroxisome proliferator-activated receptor-gamma-caspase-8-mediated cell apoptosis, kidney remodelling and hypertension." (PMID 41325840, 2025). "The levels of cleaved-caspase 3/caspase 3, cleaved-caspase 8/caspase 8, Bax/Bcl2, LC3 II/LC3 I, Beclin-1 and autophagy related 7 (ATG7) were increased in the heart of HSD rats with hypertension (HTN), and in hypertension-prone (HP) and hypertension-resistant (HR) rats." (PMID 33996809, 2021). "Our results indicated the new finding that EGCG treatment was able to prevent the early aged hypertension-activated Fas-mediated Caspase-dependent neural apoptotic pathway, as evidenced by the down-regulated levels of FasL, Fas, FADD, Caspase-8, and Caspase-3 in the hypertensive cerebral cortex." (PMID 34456710, 2021). "Our present study demonstrated that exercise training played a significant role in inhibiting hypertension-induced Fas/FasL-mediated caspase-dependent apoptotic pathway in the cerebral cortex, as indicated by decreased expression levels of FasL, Fas, FADD, active Caspase-8, and active Caspase-3." (PMID 34432648, 2021).
prostate tumor (8 papers, 2014 to 2025). "rs700635[C] is also associated with failures to correctly splice out CASP8 intron 8 in breast and prostate tumours and in corresponding normal tissues." (PMID 26740556, 2016). "In order to further illuminate the mechanism of MRV induced apoptosis in hypoxic prostate tumor cells, we determined the activation status of caspase 8 and caspase 9 in MRV-infected hypoxic DU145 cells." (PMID 24504474, 2014). "Moreover, the interaction of tumor suppressor prostate apoptosis response-4 with GRP78 at the cell surface has been shown to induce apoptosis of prostate tumor cells via ER stress and activation of the caspase 8/3 pathway." (PMID 35661704, 2022).
retinal detachment (8 papers, 2011 to 2024). An eye emergency condition which may lead to blindness if left untreated. "So, the detection and quantification of cleaved caspase 8 can be used as a marker of photoreceptor death after experimental retinal detachment and to assess the efficacy of neuroprotective agents." (PMID 37242488, 2023). "Caspase activation, including caspase 8, increases 3 days status post experimental retinal detachment and has been validated to be a marker of photoreceptor apoptosis and the extent of retinal-detachment-induced photoreceptor cell death." (PMID 37242488, 2023). "Analogous to the in vitro results, retinal detachment-induced caspase 8 activation was inhibited by ML-265 treatment in a dose-dependent manner as compared to DMSO treated eyes." (PMID 32076076, 2020). "At 3 days after experimental retinal detachment, caspase 8 activity was statistically significantly less in the Pkm2−/− mice as compared to Pkm2+/+ mice." (PMID 29259242, 2017). "Three days after retinal detachment, caspase 3, caspase 8 and caspase 9 were significantly activated in the detached retina." (PMID 24040416, 2013). "In experimental models of retinal detachment, although enzymatic activities of caspase-8, -9, -3, and -7 increase in the retina after retinal detachment, caspase inhibition by a pan-caspase inhibitor fails to prevent photoreceptor loss." (PMID 21670490, 2011). "We previously demonstrated that a small peptide antagonist of the Fas receptor (Met12) inhibits Fas-induced Caspase 8 activation and cell death of photoreceptors and retinal pigment epithelial cells in models of retinal detachment and NaIO3 model of oxidative stress respectively." (PMID 31570110, 2019). "In support of this hypothesis is the finding that this apoptotic pathway, including FAS, FASLG, and CASP8, are activated in Brown-Norway rats after retinal detachment." (PMID 24367709, 2013). "Our previous works have shown that in mouse models of retinal detachment and AMD, treatment by Met12, a precursor molecule to INL1204, inhibited Fas-mediated caspase 8 activation, and reduced activities of caspase 3 and caspase 9 as well." (PMID 39117629, 2024).
acute lymphoblastic leukemia (7 papers, 2010 to 2025). Leukemia with an acute onset, characterized by the presence of lymphoblasts in the bone marrow and the peripheral blood. "Prior work has demonstrated that caspase-1 is involved in galectin-9-mediated apoptosis of the MOLT-4 lymphoblastic leukemia cell line; we found that caspase 8 mediated antigen induced cell death of HCV-specific CTLs." (PMID 20209097, 2010). "Indeed, GB elicited an increase of TNF-α production, caspase-8 and caspase-3 activation, and PARP-1 cleavage within pre-B acute lymphoblastic leukemia Nalm-6 cells." (PMID 24039967, 2013). "Effects on acetylation of histone H3 by PCI-24781 were also examined in acute lymphocytic leukemia (ALL) cells and in variants lacking caspase-8 or FADD, and revealed a lower degree of histone H3 acetylation in the latter lines." (PMID 20145726, 2010).
cutaneous melanoma (7 papers, 2012 to 2024). A primary melanoma arising from atypical melanocytes in the skin. "The most highly significant association was between CASP8 expression and “Other malignant neoplasms of skin”." (PMID 38589365, 2024). "A six-nucleotide insertion/deletion variant rs3834129, which is located in the CASP8 promoter region, is associated with decreased risk of various cancers including cutaneous melanoma." (PMID 30906769, 2019). "Cd treatment promoted the growth of uveal and cutaneous melanoma cells due to the markedly reduced expression of p16INK4A and caspase-8 in the uveal and cutaneous melanoma cells, respectively." (PMID 36497250, 2022). "Conversely, high expression of PANoptosis genes was beneficial in skin cutaneous melanoma (SKCM), with ZBP1, NLRP1, CASP8 and GSDMD expression consistently having positive prognostic effects." (PMID 36329783, 2022).
oral squamous cell carcinoma (7 papers, 2016 to 2025). "We further examined whether JTT affects carcinoma cells using the oral squamous cell carcinoma line OSC-19 stimulated with TRAIL, which binds to DR4/DR5 and activates extrinsic apoptosis via DISC and caspase-8." (PMID 41304903, 2025).
skin cancer (7 papers, 2018 to 2025).
systemic lupus erythematosus (7 papers, 2015 to 2024). An autoimmune multi-organ disease typically associated with vasculopathy and autoantibody production. "As presented in this work, GM extract attenuates lupus-associated cardiac apoptosis in lupus-prone mice by down-regulating TNF-α/TNF-α receptors and Fas/FADD and reducing amounts of activated caspase-9, Bax, activated caspase-8 and activated caspase-3." (PMID 25985203, 2015). "An aggressive systemic lupus erythematosus (SLE)-like disease develops in mice following myeloid cell–specific deletion of Fas (CreLysMFasfl/fl) or dendritic cell (DC)-specific deletion of caspase-8 (CreCD11cCasp8fl/fl)." (PMID 26471282, 2015).
asthma (6 papers, 2020 to 2025). "(quality score 7) investigated potential drug targets through MR and found a causal protective role of ST2, a member of the interleukin 1 receptor (IL‐1R) family, against asthma and a positive association between CASP‐8 and the risk of asthma." (PMID 36434743, 2022). "This systematic review found casual effects of BMI, pubertal timing, linoleic acid, alcohol, MDD, immune related proteins ST2, IL1R, CASP‐8, IL6R and BTN3A2 on asthma risk." (PMID 36434743, 2022). "Few other studies have investigated the effect of CASP‐8 on asthma." (PMID 36434743, 2022). "However, mice with an IL-1R1 deficiency on radioresistant lung epithelial cells fail to raise a TH2 immune response and do not develop house dust mite-induced asthma, whereas caspase 8-mediated IL-1 activity promotes TH2 immunity and contributes to the development of asthma pathogenesis." (PMID 33584721, 2020).
autoimmune disease (6 papers, 2015 to 2025). A disorder resulting from loss of function or tissue destruction of an organ or multiple organs, arising from humoral or cellular immune responses of the individual to their own tissue constituents. "As cells of the innate immune system, and in particular macrophages, are now at the forefront of autoimmune disease pathogenesis, we examined the potential involvement of caspase-8 within this population." (PMID 26471282, 2015). "In addition, CASP8 has shown its significance in certain autoimmune diseases and neurodegenerative disorders, where it may be involved in regulating inflammatory responses or affecting the survival of neuronal cells." (PMID 38186679, 2023).